ZNF442 (zinc finger protein 442)
Description:
May be involved in transcriptional regulation.
Synonyms: FLJ14356
Tractability: PROTAC: ubiquitination databases record sites on it.
Gene: Protein-coding gene on chromosome 19 (12,345,944 to 12,365,905, reverse strand). Ensembl gene ENSG00000198342.
Subcellular location: Nucleus
Subcellular location (Human Protein Atlas): Nuclear membrane; Vesicles
Pathways (Reactome):
Gene expression (Transcription): Generic Transcription Pathway
Gene Ontology:
Molecular function: DNA-binding transcription factor activity, RNA polymerase II-specific; RNA polymerase II transcription regulatory region sequence-specific DNA binding
Biological process: regulation of transcription by RNA polymerase II; regulation of DNA-templated transcription
Cellular component: nucleus
Genetic constraint (gnomAD): Loss-of-function variants: 45 observed, 59.94 expected, observed/expected ratio (o/e) 0.75, 90% interval 0.59 to 0.96. The upper end of that interval is the gene's LOEUF score, 0.96, which puts it in group 4 of 6, group 1 being the genes least tolerant of losing a copy. Missense variants: 690 observed, 786.57 expected, observed/expected ratio (o/e) 0.88, 90% interval 0.82 to 0.93. Synonymous variants: 213 observed, 253.06 expected, observed/expected ratio (o/e) 0.84, 90% interval 0.75 to 0.94.
Homologues: Orthologues: chimpanzee ZNF442 (98% identical), rat Zfp617 (30% identical), mouse Zfp961 (30% identical). Paralogues in human: ZNF443 (73% identical), ZNF799 (73% identical), ZNF823 (72% identical), ZNF44 (70% identical), ZNF441 (56% identical), ZNF700 (53% identical), ZNF709 (53% identical), ZNF563 (52% identical), ZNF433 (51% identical), ZNF14 (47% identical), ZNF791 (47% identical), ZNF878 (44% identical), and 3 more.
Diseases named in the same sentence as ZNF442 in open-access papers:
ZNF442 is named in the same sentence as 2 diseases in open-access papers, as found by Europe PMC text mining. Sharing a sentence is not in itself a finding about the gene and the disease. The quoted sentences say what the papers report.
breast cancer (1 paper, 2023). A primary or metastatic malignant neoplasm involving the breast. "ZNF442 plays a role in the strategy adopted by ER+ BC and triple-negative breast cancer (TNBC) cell lines for maintaining zinc homeostasis." (PMID 37715225, 2023).
ZNF442 also shares sentences with these, for which no sentence is quoted: triple-negative breast carcinoma (1 paper).